ZNF154 (zinc finger protein 154)
Diseases named in the same sentence as ZNF154 in open-access papers (continued):
Sharing a sentence is not in itself a finding about the gene and the disease.
asthma (1 paper, 2021). "Only in the case of asthma were the methylation levels at ZNF154 significantly higher than that of the normal control epithelial cells." (PMID 33420235, 2021).
Cirrhosis (1 paper, 2025). A chronic disorder of the liver in which liver tissue becomes scarred and is partially replaced by regenerative nodules and fibrotic tissue resulting in loss of liver function. "Notably, EID3, MIR150, and ZNF154 have been reported to exhibit differential expression between cirrhosis patients and HCC patients, suggesting their potential as biomarkers for early-stage HCC." (PMID 40500793, 2025).
Crohn disease (1 paper, 2021). A gastrointestinal disorder characterized by chronic inflammation involving all layers of the intestinal wall, noncaseating granulomas affecting the intestinal wall and regional lymph nodes, and transmural fibrosis. "While methylation array data derived from tissues of the gastrointestinal tract indicated elevated methylation at ZNF154, patients with Crohn’s disease or ulcerative colitis actually had reduced methylation levels relative to healthy controls." (PMID 33420235, 2021).
endometrial cancer (1 paper, 2023). Primary or metastatic malignant neoplasm involving the endometrium (mucous membrane that lines the endometrial cavity). "In 2013, Sánchez-Vega and coworkers found ZNF154 hypermethylation and downregulation to be one of the most common epigenetic changes in ovarian and endometrial cancers, and subsequently, across 15 distinct solid cancer types from the TCGA." (PMID 37254212, 2023).
esophageal cancer (1 paper, 2022). A primary or metastatic malignant neoplasm involving the esophagus. "We used the GEPIA software to analyze the correlation between the expression of these genes and ZNF154 in esophageal cancer, and found that 12 genes correlated with the expression of ZNF154." (PMID 36064578, 2022).
liver cirrhosis (1 paper, 2023). "Persistent hypermethylation of the ZNF154 and ZNF540 genes, as well as CCL20 hypomethylation, were registered in tumor tissue in relation to both liver fibrosis and liver cirrhosis." (PMID 36923478, 2023).
lung carcinoma (1 paper, 2023). "With these thresholds, the ZNF154 locus displayed the best performance of any single marker in lung cancer plasma with an AUC of 0.78 enabling a sensitivity of 77.8%." (PMID 37835520, 2023).
nasopharyngitis (1 paper, 2017). An inflammatory process that affects the nasopharynx. "Quantitative RT-PCR revealed ZNF154 was expressed in the normal nasopharyngeal cell line NP69 and non-cancer nasopharyngitis biopsy tissues, whereas absent or reduced expression of ZNF154 was observed in the eight NPC cell lines and human NPC tissues." (PMID 29156753, 2017).
oral cancer (1 paper, 2023). "First, it was not possible to express a full length ZNF154 or ZNF132 construct within oral cancer UM-SCC-1 cells in order to identify possible downstream targets of these proteins in the cancer cell environment." (PMID 37254212, 2023).
pancreatic adenocarcinoma (1 paper, 2021). "Notably, our ZNF154 methylation detection method achieved 100% sensitivity and 80% specificity when used on plasma from patients with early-stage pancreatic adenocarcinoma, encouraging future studies to validate its effectiveness in early stage tumors." (PMID 33420235, 2021).
cancer (23 papers, 2015 to 2025). A tumor composed of atypical neoplastic, often pleomorphic cells that invade other tissues. "ZNF154 hypermethylation was less frequent than the combinations of cancer-associated gene mutations in only two cancer types." (PMID 33420235, 2021). "For all other tumor types investigated (9 out of 11), however, ZNF154 hypermethylation was more common than cancer-associated gene mutations." (PMID 33420235, 2021). "Importantly, we demonstrated a higher incidence of ZNF154 hypermethylation compared to panels of somatic driver mutations, underscoring the utility of a multi-cancer, DNA methylation biomarker." (PMID 37835520, 2023). "On the basis of our previous results, we hypothesized that ZNF154 hypermethylation would occur more frequently in individual cancer types than the most common cancer mutations." (PMID 33420235, 2021). "Thus, we concluded that ZNF154 hypermethylation can be at least as recurrent as the most common cancer-associated mutations, making it a biomarker worthy of further investigation." (PMID 33420235, 2021). "For example, our lab previously identified a DNA methylation marker in the ZNF154 promoter as a putative pan-cancer biomarker." (PMID 41000959, 2025). "Previously, we showed that ZNF154 is a multi-cancer biomarker whose differential methylation demonstrates potential clinical utility for tumor diagnostics." (PMID 41000959, 2025). "Alternatively, ZNF154 has been reported to discern cancer patients, including those with pancreatic, colorectal, and liver malignancies, from healthy controls; however, such testing inherits intrinsic limitations to specificity." (PMID 39409954, 2024). "Other studies with hypopharynx cancers suggest that ZNF154 has tumour-suppressive action by inhibiting the Wnt/β-catenin signalling pathway activation and suppressing epithelial-mesenchymal transition." (PMID 37254212, 2023). "Compared to classification by ZNF154 alone, the sensitivity of detection of the 14 cancer types improved with the three-marker combination, except uterine and prostate, which stayed the same (99% and 90%, respectively)." (PMID 37835520, 2023). "The importance of ZNF154 in cancer is further highlighted by recurring reports of its hypermethylation in several other malignancies, including bladder, breast, lung, ovarian, renal and prostate." (PMID 37254212, 2023). "ZNF154 methylation has most recently been documented in plasma samples from early-stage cancer patients, suggesting it as a promising target in liquid biopsy." (PMID 37254212, 2023). "Previously, we reported a promising multi-cancer methylation biomarker, ZNF154, which is hypermethylated in at least 14 different cancer types in The Cancer Genome Atlas (TCGA) of tumor data." (PMID 37835520, 2023). "To identify additional markers with similar performance to ZNF154 across multiple cancer types, we reanalyzed TCGA data from the same 14 cancer types." (PMID 37835520, 2023). "In order to assess further the absence of tumour DNA in the cervical smear samples we used MethyLight, a real time PCR-based method, to amplify methylated ZNF154, a pan-cancer marker primarily discovered in ovarian cancer." (PMID 35105887, 2022). "We assessed the effectiveness of hypermethylation at the CpG island of ZNF154, a previously reported multi-cancer specific signature for use in a blood-based cancer detection assay." (PMID 33420235, 2021). "One important difference between ZNF154 methylation and CancerSEEK is the ability of CancerSEEK to localize cancer to a small number of anatomic sites in a median of 83% of patients, which ZNF154 methylation cannot do." (PMID 33420235, 2021). "ZNF154’s performance at identifying plasma samples from patients with cancer is competitive with that of other proposed biomarkers." (PMID 33420235, 2021).
cancer (continued). "In future studies, we plan to investigate ZNF154 methylation in larger validation sets of plasma samples from patients with cancer of different types and stages, as well as larger control sample cohorts." (PMID 33420235, 2021). "We used these data to perform in silico simulations using methylation density profiles from individual epiallelic copies of ZNF154, a genomic locus known to be recurrently methylated in numerous cancer types." (PMID 33081832, 2020). "Generally, ZNF154 promoter hypermethylation has been found in several cancer entities and was suggested for screening." (PMID 31683647, 2019). "Hypermethylation and low expression levels of ZNF154 have been considered promising biological markers for tumor identification and cancer recurrence surveillance." (PMID 27716329, 2016). "In particular, ZNF154 - which we recently proposed as a pan-cancer biomarker to distinguish tumors from non-cancer controls - was also part of this collection." (PMID 25960768, 2015). "Previously, zinc fingers methylation could be used to diagnose cancer (e.g., ZNF154), we further indicate a potential contribution of methylation to alternative RNA expression." (PMID 38720348, 2024). "We previously showed that ZNF154 probe cg21790626 (hg19/chr19:58,220,494) in Illumina’s 450 K methylation array is significantly hypermethylated in 4050 TCGA tumor vs. 646 normal samples from 14 cancer types." (PMID 37835520, 2023). "In conclusion, our research indicates that ZNF154 methylation testing in plasma may be a method capable of detecting multiple cancer types." (PMID 33420235, 2021). "Thus far in our analyses, ZNF154 shows promise as a pan-cancer biomarker suitable for blood-based screening." (PMID 33420235, 2021). "In this proof-of-concept study, we set out to determine whether ZNF154 methylation appears to be a suitable biomarker for a multi-cancer, plasma-based screen." (PMID 33420235, 2021). "Furthermore, the potential utility of ZNF154 as a pan-cancer methylation biomarker also afforded the opportunity to directly compare the performance of EpiClass in different cancer types." (PMID 33081832, 2020). "ZNF154 and ZNF577 downregulation has been reported to be associated with several cancers." (PMID 28174608, 2017). "Using CAMDAC cancer-cell-specific methylomes as input for MethSig, we observed significant enrichment of hypermethylated candidate NSCLC cancer genes known to encode differentiation and developmental transcription factors, such as PCDHGA3 and EVX1, and in ZNF-154, which may affect plasticity." (PMID 40931149, 2025). "However, as some tumors were missed by the marker, we predicted that cancer detection by ZNF154 could be improved by combination with additional multi-cancer methylation biomarkers." (PMID 37835520, 2023). "A CpG island chr19:58220189–58220517 was significantly hypermethylated in all four cancer types and strongly correlated with the downregulation of transcription regulator zinc finger protein 154 (ZNF154), which could serve as a potential epigenetic therapeutic biomarker." (PMID 36861126, 2023). "In addition to verifying that ZNF154 methylation is elevated in the plasma of patients with cancer, it is important to establish that methylation of this gene is not correlated with demographic factors such as age or sex, as previous studies have found for other loci." (PMID 33420235, 2021). "Thus, in this proof-of-concept study, we set out to determine whether ZNF154 methylation is a suitable biomarker for a multi-cancer, plasma-based screening test." (PMID 33420235, 2021). "We further investigated the genes with the top 3 inactive core promoters: ZNF154, ZNF135, ZNF667-AS1 and ZNF667, using public data from commonly used cancer databases." (PMID 38084904, 2024). "The truncated version of ZNF154 protein increased doubling time and reduced cell migration in UM-SCC-1 cancer cells." (PMID 37254212, 2023).
cancer (continued). "Compared to ZNF154 alone, the addition of TLX1 and GALR1 into a three-marker assay improved the AUC value by more than 0.07 in 4 cancer types." (PMID 37835520, 2023). "We identify two novel, multi-cancer markers in the intronic or promoter regions of TLX1 and GALR1, respectively, and report the benefit of combining them with ZNF154 as a multi-cancer assay." (PMID 37835520, 2023). "To summarize each marker, we found the average of the sensitivity values in tissue samples across all 14 cancer types was 78% for GALR1, 81% for TLX1, and 84% for ZNF154." (PMID 37835520, 2023). "Real-time PCR was performed to check the methylation difference of HOXD9, ZNF154, BCL9, TDRD10, and ANKRD53 genes between the cancer cases and controls." (PMID 34452548, 2021). "The identification of SENP7-regulated genes such as ZNF154 potentially extends the understanding of SENP7 function and linkages to cancer processes." (PMID 25716334, 2015). "We leveraged public data from diverse popular cancer projects and found a decrease in the expression of putative housekeeping tumor suppressor genes (ZNF154, ZNF135, ZNF667, and ZNF667-AS1) due to aberrant methylation of their core promoters in several cancer subtypes." (PMID 38084904, 2024). "By comparison, ZNF154, which was not originally identified using this method, met the 0.40 threshold in only six cancer types: bladder, head and neck, liver, lung squamous cell, stomach, and uterine." (PMID 37835520, 2023). "From these results, we concluded that even when expressed as a partial sequence, ZNF154 peptide reduced doubling time for UM-SCC-1 cancer cells while neither full length ZNF protein had significant effect on growth of HEK-293 cells." (PMID 37254212, 2023). "It will also be important to confirm that ZNF154 methylation is not elevated in the plasma of patients with non-cancer diseases." (PMID 33420235, 2021). "Our results suggest that EpiClass can be successfully implemented with ZNF154 cfDNA methylation data obtained by different methods (RRBS, WGBS, DNA melting data via DREAMing) to improve liquid-biopsy-based detection of disparate cancer phenotypes." (PMID 33081832, 2020). "Finally, for the set of putative housekeeping tumor suppressor genes (ZNF135, ZNF154, ZNF667 and ZNF667-AS1), e.g. genes whose HK-CPs are active in less than 20% of the cancer cells, we performed a comprehensive analysis using cancer samples of 17 projects from TCGA." (PMID 38084904, 2024). "Thus, we concluded that, with rare exceptions, ZNF154 is not hypermethylated (i.e., compared to normal) in non-cancer conditions we examined." (PMID 33420235, 2021). "While we were able to express full-length ZNF154 and ZNF132 constructs in HEK-293 cells without issue, attempts to express these same constructs in head and neck UM-SCC-1 cancer cells resulted in truncated proteins lacking partial internal amino acid sequences." (PMID 37254212, 2023).
tumor (22 papers, 2012 to 2026). "Consistent with their roles as tumor suppressors, we found that low expression of either ZNF154 or ZNF132 were significantly associated with a worse overall survival in 508 HNSCC patients." (PMID 37254212, 2023). "Further analysis revealed the tumor-suppressive function of ZNF154 was closely associated with the EMT." (PMID 29156753, 2017). "In previous reports, HOXA9 and ZNF154 methylation has been associated with tumour recurrence, and ISL1 methylation with tumour progression in predominantly low/intermediate-grade tumours." (PMID 26332997, 2015). "Survival analysis stratifying patients based on this criterion demonstrated that patients whose primary tumours had higher ZNF154 expression showed a significantly better overall survival when compared to the remaining cohort (Log-rank, p < 0.05)." (PMID 37254212, 2023). "Here, we assessed methylation data for TLX1, GALR1, and ZNF154 in cell lines derived from non-tumor (n = 30) or tumor (n = 23) cell karyotypes, and in addition nine cell lines with no designation." (PMID 37835520, 2023). "As with the growth assay, overexpression of the truncated ZNF154 protein resulted in a significant decrease in tumor cell migration when compared to the empty vector control cells." (PMID 37254212, 2023). "The assay with the highest correct classification of tumor samples was TLX1 combined with ZNF154 and the triple marker assay, both of which reached 79% sensitivity across all tumor samples." (PMID 37835520, 2023). "Previously, we applied this approach using tumor and normal tissue DNA methylation signal at the ZNF154 locus to predict the suitability of this marker for liquid biopsy analysis." (PMID 37835520, 2023). "The difference in median beta value between tumor and normal samples for colon was 0.13 for ZNF154, while TLX1 and GALR1 showed a difference of 0.70 and 0.60, respectively." (PMID 37835520, 2023). "From these and the previous results, it appeared that even the truncated version of ZNF154 retained some biological activity resulting in the reduction in both growth and tumor cell migration." (PMID 37254212, 2023). "Our further studies clarified the role of some aberrantly methylated genes in tumor progression, such as ZNF154 (encoding zinc finger protein 154) and SFRP1 (encoding secreted frizzled related protein 1), which act as antioncogenes to inhibit NPC metastasis." (PMID 35410462, 2022). "To determine the prognostic relevance of ZNF154 promoter hypermethylation, we analyzed the methylation ratios in the tumor tissues from 78 ESCC patients, of which 42 patients had been regularly followed-up." (PMID 36064578, 2022). "These beta value cutoffs values ranged from 0.016 to 0.523 with a median value of 0.161; using these cutoffs, we found that ZNF154 was hypermethylated in 50.6–98.6% of tumor samples, depending on the tumor type (for example, 52% PRAD and 92.4% OV)." (PMID 33420235, 2021). "For all but 2 tumor types investigated, ZNF154 was significantly hypermethylated with respect to control samples (p < 0.001)." (PMID 33420235, 2021). "For reference, we compared the ZNF154 methylation levels seen in control and tumor tissues from our preceeding TCGA analyses." (PMID 33420235, 2021). "We found that if ZNF154 methylation was quantified using the average methylation levels in each sample, tumor signals in plasma often went undetected because of background signals in control samples." (PMID 33420235, 2021). "Future research in different tumor entities should target patient survival in relation to methylated ZNF154 as well." (PMID 31683647, 2019). "Recent research has disclosed DNA promoter hypermethylation of the zinc finger protein ZNF154 in a variety of tumor cell lines." (PMID 31683647, 2019).